GATA2 (GATA binding protein 2)
Diseases named in the same sentence as GATA2 in open-access papers (continued):
Sharing a sentence is not in itself a finding about the gene and the disease.
leukemia (continued). "In light of these findings, we asked whether elevated CEBPA level and not the CEBPA mutation(s) per se, drives the selective pressure for GATA2 and/or TET2 loss in AML to achieve moderate GATA2 levels that are optimal for leukemia growth." (PMID 37794021, 2023). "In addition, the rearrangement of chromosome 3q results in distal GATA2 enhancer translocation, which activates the expression of EVI1 and causes functional haploinsufficiency of GATA2 in leukemia, both of which are driven by chromosomal remodeling." (PMID 35277481, 2022). "Moreover, some gene mutations are involved, and GATA2 and SMAD4 mutations were identified when the disease progressed from myelodysplastic syndrome to leukemia." (PMID 36181538, 2022). "The up-regulation of these genes by GATA2 activation may play a tumor-promoting role in leukemia and reinforce the potential function of GATA2 in leukemogenesis in B-ALL." (PMID 35087776, 2021). "However, despite slower development of leukemia, the Cbfb-MYH11 Gata2-deficient mice showed a more aggressive phenotype at the leukemic stage." (PMID 31817911, 2019). "Heterozygous knockout of Gata2 in Cbfb-MYH11 mice delayed leukemia onset." (PMID 31817911, 2019). "To address whether GATA2 could act as a regulator of chemotherapy resistance in human leukemia cells, we observed KG1a cells and clinical patients’ AML cells with a classic drug (Cerubidine) and Gefitinib." (PMID 28114350, 2017). "ChREBP and its downstream molecules, including TXNIP, RUNX1 and GATA2, may be ideal therapeutic targets for certain types of leukemia." (PMID 27224916, 2016). "Results from in vivo serial transplants of these cells into NSG-S mice suggest that germline GATA2 mutation alone is not sufficient to promote leukemia, however in combination with SETBP1+ASXL mutations a higher engraftment potential was observed in secondary transplants." (PMID 34633564, 2021). "We hypothesized that GATA2-associated leukemia does not develop as a primary event but rather occurs as a secondary event after BM failure." (PMID 34633564, 2021). "As a consequence, GATA2 alone is not sufficient to inhibit CBFβ-MYH11-caused leukemia, and it maybe has greater functional relevance only in context with overexpression of other regulators like KLF1." (PMID 30850577, 2019). "Common leukemia-associated genes have been identified by the investigation of gene sets obtained by comparison of analysis 1 with analysis 3 [FLT3 and C-terminal binding protein 2 (CTBP2)] and analysis 2 with analysis 3 [NRAS and GATA binding protein 2 (GATA2)]." (PMID 29221109, 2017). "Interestingly, there exist dose effects of both RUNX1 and GATA2 in leukemia development because either too low or too high levels of these proteins significantly influence the initiation, maintenance and relapse of leukemia." (PMID 27224916, 2016). "These splicing perturbations alter the composition of numerous hematopoietic stem and progenitor (KLF2, GATA2, GATA1, SPINK2) or leukemia (LAT2 and NUCB2) regulatory factors." (PMID 36697445, 2023). "We examined the RNA expression of three hematopoietic GATA transcription factors (GATA1, GATA2, and GATA3) in a total of 1,644 pediatric leukemia patients with AML (n = 297), T-ALL (n = 99), and B-ALL (n = 1,248) using RNA-seq data available at St." (PMID 35087776, 2021). "TCFL5 has been previously shown to be upregulated in E/R+ pre-B-ALL, while GATA2 has been reported to contribute to the upregulation of erythroid genes, such as EPOR, a known marker gene in E/R+ leukemia." (PMID 33218352, 2020). "A subset of mice lacking one allele of Gata2 in endothelial cells display a dilated thoracic duct with reduced lymph flow, but they have a normal lifespan and do not develop any obvious symptoms of the human disease, such as leukemia, bacterial infections or warts (our unpublished observations)." (PMID 31582413, 2019).
leukemia (continued). "In leukemia, ERG targets transcription factors such as GATA2, which is an important regulator of hematopoietic stem cell and megakaryocyte development and, RUNX1, which is involved in the development of normal hematopoiesis." (PMID 30303964, 2018). "We used mutations commonly found in patients with leukaemia, myelodysplastic syndrome (MDS) and ES, that were reported to interfere with DNA-binding affinity of GATA2, to implicate the requirement for the C-ZF, but not the N-ZF for mitotic retention." (PMID 37580379, 2023). "We here identify GATA-2 as a “non-canonical” chromatin regulator that is able to selectively control access to lineage-specific TFs motifs, thereby controlling the phenotype of the resulting leukemia." (PMID 32330454, 2020). "Consistently, RUNX1, but not GATA2, was remarkably upregulated in ChREBP-null leukemia cells, which could be partially suppressed by the ectopic expression of TXNIP." (PMID 27224916, 2016). "Acute lymphoid leukaemia patient samples show overlapping, yet on average even lower levels of GATA2 than AML (data not shown) suggesting that the incompatibility of high GATA2 expression with leukaemia development may extend beyond AML." (PMID 21297973, 2011).
myelodysplastic syndrome (73 papers, 2013 to 2026). A clonal hematopoietic disorder characterized by dysplasia and ineffective hematopoiesis in one or more of the hematopoietic cell lines. "GATA2 deficiency predisposes patients to recurrent infections, myelodysplastic neoplasms (MDSs), and malignancies through disrupted hematopoiesis and immune dysfunction." (PMID 42196275, 2026). "In humans, germline mutations in GATA2 lead to GATA2 Deficiency, a heritable disease that combines immunodeficiency with myelodysplastic syndrome, and somatic mutations are observed in 1–4% of patients with myeloid malignancies." (PMID 41318785, 2025). "GATA2 deficiency is one of the most common genetic predispositions to pediatric myelodysplastic syndrome (MDS) in children and adolescents." (PMID 38993648, 2024). "GATA2 deficiency is one of the most common genetic predispositions to myelodysplastic syndrome (MDS), accounting for 7% of all pediatric patients diagnosed with MDS initially thought to be de novo." (PMID 38993648, 2024). "Mutation of GATA2 has been associated with congenital neutropenia and MonoMAC syndrome, a disorder that frequently results in myelodysplastic syndrome (MDS), increased rate of infections and AML or chronic myelomonocytic leukemia." (PMID 34066700, 2021). "GATA2 deficiency is a heterogeneous multi-system disorder characterized by a high risk of developing myelodysplastic syndrome (MDS) and myeloid leukemia." (PMID 34244664, 2021). "Deficiency of the transcription factor GATA2 is a highly penetrant genetic disorder predisposing to myelodysplastic syndromes (MDS) and immunodeficiency." (PMID 32555368, 2020). "GATA2 deficiency is considered one of the most common cancer predisposition syndromes determining myelodysplastic syndrome in children." (PMID 33066218, 2020). "GATA2 loss of function mutations cause immunodeficiency syndromes that progress to myelodysplastic syndrome and AML on acquisition of secondary mutations." (PMID 31434974, 2019). "In this review, we describe GATA2 deficiency clinical presentation in order to focus on phenotypes that, in patients with myelodysplastic syndrome, may be suggestive of GATA2 deficiency." (PMID 33066218, 2020). "Clinically, GATA2 deficiency has been known to be a major predisposition to myelodysplastic syndrome (MDS)." (PMID 41438140, 2025). "GATA2 deficiency is an autosomal dominant transcriptopathy disorder with high risk for myelodysplastic syndrome (MDS)." (PMID 40664679, 2025). "Moreover, it is essential to appreciate that rheumatological manifestations may precede or overshadow the more notorious GATA2 deficiency associated infectious and myelodysplastic syndromes 1,2." (PMID 32433473, 2020). "Lower amounts of Gata2 caused by mutations contribute to the development of myelodysplastic syndrome (MDS) and AML44." (PMID 30842549, 2019). "GATA2 gene mutations that predisposed to myelodysplastic syndrome (MDS)and acute myeloid leukaemia (AML) were reported." (PMID 26953528, 2016). "Overall, 16 patients (17.2%) had pathogenic variants, including FANCA, BRCA2, PMS2, ELANE, G6PC3 and VPS13B in patients with idiopathic neutropenia, and GATA2 in patients with suspected myelodysplastic syndrome." (PMID 40358701, 2025). "Tumor nuclei were either negative or positive for GATA2, which is a pattern of GATA2 expression that we have previously reported in benign and premalignant uterine tissues, as well as in myelodysplastic neoplasms and acute leukemias in the bone marrow." (PMID 40168074, 2025). "GATA2 mutations usually present as germline variants and have been known to predispose to AML and myelodysplastic syndromes." (PMID 39922030, 2024). "In the pediatric age group, germline abnormalities in GATA2, SAMD9, and SAMD9L are the most common causes of myelodysplastic neoplasms and AML." (PMID 39062641, 2024). "GATA2 is known to be dysregulated through genetic mutations or epigenetic silencing in subsets of AML and myelodysplastic syndrome." (PMID 28060870, 2017).
myelodysplastic syndrome (continued). "In addition to immune deficiency, GATA2 deficiency is a cause of familial bone marrow failure, and a recent study of over 400 children and adolescents revealed GATA2 mutation to be the most common germline mutation leading to myelodysplastic syndrome in children and young adults." (PMID 27994588, 2016). "GATA2 deficiency syndrome should be considered in patients with myelodysplastic syndrome, nontuberculous mycobacterium infection and HLH." (PMID 38730328, 2024). "Here we report a patient with GATA2 deficiency that presented with disseminated non-tuberculous mycobacterial infection and pancytopenia secondary to myelodysplastic syndrome." (PMID 36937639, 2023). "Moreover, due to the lack of clear guidelines, we performed an overview on literature data regarding management of GATA2-related myelodysplastic syndrome, in order to understand the best choice of treatment for these patients." (PMID 33066218, 2020). "Whole-genome sequencing (WES) of peripheral blood did not detect mutations in the ELANE or GATA2, typically associated with cyclic neutropenia or myelodysplastic syndrome (MDS)." (PMID 39781543, 2024).
Immunodeficiency (63 papers, 2014 to 2026). Failure of the immune system to protect the body adequately from infection, due to the absence or insufficiency of some component process or substance. "GATA2 deficiency is a unique primary immune deficiency, also known as immunodeficiency 21, DCML, or monoMAC (OMIM #614172)." (PMID 41322420, 2025). "Mutations in the GATA2 gene can result in a range of diseases, predominantly marked by immunodeficiency and hematological disorders." (PMID 41154393, 2025). "Germline heterozygous mutations in GATA2 present with a spectrum of phenotypes, from mild cytopenia to severe immunodeficiency, and often progress to advanced myeloid neoplasia and life-threatening infections, requiring timely stem cell transplantation." (PMID 40358701, 2025). "While GLILD is primarily associated with common variable immunodeficiency, rare cases have linked it to GATA2 deficiency, making it an uncommon but clinically important pulmonary complication in this setting." (PMID 40981111, 2025). "GATA2 deficiency, a syndrome caused by heterozygous loss-of-function variants in the GATA2 gene, is characterized by immunodeficiency, bone marrow failure, and predisposition to myeloid neoplasms." (PMID 40821825, 2025). "Individuals carrying GATA2 mutations are prone to develop immunodeficiency and BMF, which can progress to MDS and AML." (PMID 41249190, 2025). "This case highlights the aggressive nature of SCC in the context of GATA2 deficiency and underscores the importance of genetic testing in patients with unusual malignancy presentations and suspected immunodeficiency." (PMID 39981594, 2025). "Heterozygous GATA2 mutations manifest as hematologic, infectious, pulmonary, dermatologic, neoplastic, and vascular/lymphatic diseases, but immunodeficiency remains the hallmark feature of GATA2 deficiency." (PMID 39981594, 2025). "This variability extends to immune disfunctions, as GATA2-MDS has been frequently associated with overlapping immunodeficiencies." (PMID 40299403, 2025). "Mutations in the GATA2 gene can manifest as various clinical presentations, but they are primarily considered immune system disorders and bone marrow abnormalities." (PMID 40797383, 2025). "The absence of post-transplant complications is a good sign; however the long-term prognosis remains uncertain due to the presence of GATA2 deficiency, which warrants regular check-ups and can cause extramedullary manifestations and immune dysfunction." (PMID 40981111, 2025). "Germline GATA2‐deficiency usually manifests as immunodeficiencies and myeloid neoplasms and sometimes with dermatological diseases, including warts, panniculitis, and skin cancers." (PMID 39614632, 2024). "On the contrary, the occurrence of pneumocystis jiroveci pneumonia has been rare, highlighting the considerable heterogeneity of the immunodeficiency spectrum in GATA2 deficiency." (PMID 38993648, 2024). "Germline GATA2 variants induce primary immunodeficiency and increase susceptibility to infections due to immune dysfunction, which is probably responsible for the high incidence of solid cancers." (PMID 39614632, 2024). "The patient also had B and NK cell deficiency, which was consistent with GATA2-associated immunodeficiency." (PMID 37325673, 2023). "As a result of immune deficiency, GATA2 carriers have an increased frequency of infections, with significant differences in the severity between patients." (PMID 36900380, 2023). "One of the most well-known syndromes within this group is GATA2 deficiency, which is a highly heterogeneous disorder that can include pulmonary and vascular involvement, immunodeficiency, and myeloid neoplasms." (PMID 36900380, 2023). "Mutations in GATA2 have been linked to severe B-cell lymphopenia, cytopenias, bone marrow failure, and immunodeficiency, in particular, the autosomal dominant immunodeficiency 21 (MIM# 614172)." (PMID 37959410, 2023).
Immunodeficiency (continued). "GATA2 deficiency is a unique primary immune deficiency that is also known as immunodeficiency 21, DCML, or MonoMAC (OMIM #614172)." (PMID 36900380, 2023). "Here, we describe successful bone marrow transplantation in a carrier of a novel GATA2 pathogenic variant who was diagnosed with immunodeficiency a few years after completion of B-cell precursor acute lymphoblastic leukemia (BCP-ALL) treatment." (PMID 35983050, 2022). "Germline mutations of GATA2 cause a various and complex clinical phenotype, including immunodeficiency, bone marrow failure, lymphedema, deafness, and pulmonary dysfunction." (PMID 35769478, 2022). "GATA2 haploinsufficiency causes an immune disorder that is characterized by bone marrow failure and (near) absence of monocytes, dendritic cells, B cells and natural killer (NK) cells." (PMID 36268026, 2022). "Germline mutations in the GATA2 gene, mostly arising de novo, had been reported to cause an immunodeficiency/myelodysplasia syndrome manifesting with a multitude of clinical phenotypes." (PMID 32555368, 2020). "These cause a relatively milder form of the immunodeficiency phenotype observed in germline mutant GATA2 patients, along with a common presentation of AML, atypical chronic myeloid leukemia and in some cases acute erythroid leukemia." (PMID 34713225, 2020). "Patients with germline GATA2 mutation present a wide range of immune dysfunctions, leading to severe infections, primarily generalized warts and mycobacterial infection." (PMID 33066218, 2020). "Variants were found in 73% (8/11) of patients with MDS, 71% (5/7) of patients with GATA2 deficiency related bone marrow and immunodeficiency disorder (G2BMID), and only in one subject with normal blood cells count and bone marrow histology." (PMID 33066218, 2020). "GATA2 is one of the master regulators of blood production and patients that carry a mutation in one of the two alleles of GATA2 often manifest with immunodeficiency syndromes and increased lifetime risk for MDS/AML." (PMID 34713225, 2020). "GATA2 deficiency has a broad phenotype encompassing immunodeficiency, MDS/AML, pulmonary disease, and vascular/lymphatic dysfunction." (PMID 26264606, 2015). "Other familial cases of AML with immunodeficiency and pulmonary dysfunction have also since been tracked to GATA2 mutation." (PMID 25707267, 2015). "The most common manifestations of immune dysfunction in GATA2 mutation are generalized warts and mycobacterial infection." (PMID 25707267, 2015). "Thus, our results have provided evidence for a link between GATA2 mutation and immune dysfunction in immunocompromised individuals that increase Mh susceptibility in humans." (PMID 40762982, 2025). "Furthermore, the use of conventional intensive chemotherapy in patients with GATA2-related MDS is associated with increased NRM probably because of prolonged episodes of neutropenia adding to the risk of the underlying immunodeficiency." (PMID 38993648, 2024). "The immune defect may appear in adult life, as the number of hematopoietic stem and progenitor cells (HSPCs) decreases with age, which makes GATA2 deficiency a unique primary immune deficiency." (PMID 36900380, 2023). "Additionally, somatic mutations in GATA2, although rare, have also been linked to milder forms of the immunodeficiency phenotype observed in patients with germline mutant GATA2." (PMID 36900380, 2023). "GATA2 is associated with hematopoietic and immune deficiency of COVID-19." (PMID 37877121, 2023). "Eventually, as in other immunodeficiencies, these patients can also present with autoimmune manifestations, described in 11–30% of cases, which may overshadow typical features of GATA2 deficiency and delay the diagnosis." (PMID 36900380, 2023). "GATA2 encodes a pleiotropic TF that regulates numerous genes critical for embryonic development and neuronal cell fate and haploinsufficiency results in blood and immune disorders." (PMID 37386251, 2023).